RAD51 (RAD51 recombinase)
Diseases named in the same sentence as RAD51 in open-access papers (continued):
Sharing a sentence is not in itself a finding about the gene and the disease.
tumor (continued). "However, higher levels of Rad51 were found to be associated with enhanced tumor grading of invasive breast ductal breast cancer." (PMID 25909291, 2015). "It is relevant to speculate how increased RAD51 protein levels confer radioresistance in tumor cells, especially when additional mutations are generated in DNA repair that should make them radiosensitive." (PMID 23675572, 2013). "Moreover, a high level of RAD51 expression is observed in a variety of tumor cell lines and is associated with a poor outcome in the therapy of lung cancer." (PMID 23675572, 2013). "The assessment of Rad51 expression may, therefore, be used as an additional tool in identifying those patients at risk of tumour recurrence and progression, and it may be a helpful criterion to optimise individual therapy management." (PMID 15956972, 2005). "We could demonstrate that in vitro onvansertib inhibited both HR and non-homologous end-joining repair pathways and in vivo induced a decrease in the number of RAD51 foci-positive tumor cells, supporting its ability to induce HR deficiency and favoring the activity of olaparib." (PMID 39039067, 2024). "Additionally, making HDR-proficient tumor cells HR-deficient by inhibiting RAD51 could prove useful in restoring synthetic lethality in tumors that have developed resistance with PARP inhibitors (PARPi)." (PMID 35463312, 2022). "The high levels of Rad51 may also be associated with genome instability, suggesting that the NaBut-mediated decrease in Rad51 in transformed cells may lead to overcoming the tumor’s chemoresistance." (PMID 35408878, 2022). "In addition, RAD51 expression was associated with higher tumor differentiation (P < 0.05)." (PMID 32190537, 2020). "Interestingly, a statistically significant decrease in Rad51 foci was observed in Brca2 heterozygous carriers compared to wild types, indicative of haploinsufficiency, a hypothesised cause of some tumours in patients with a germline BRCA2 mutation." (PMID 29184099, 2017). "This new mechanism may explain not only the development of tumors that lack mutations or alterations in tumor suppressors involved in DNA damage repair and response but also the overexpression of RAD51 found in a wide variety of human tumors, including BRCA1-deficient ones." (PMID 26282282, 2015). "Combining a RAD51 inhibitor with BA-BNCT significantly enhances the anti-tumor efficacy against radioresistant HCC and parental HCC cells." (PMID 40824344, 2026). "In this study, we further analyzed the expression of RAD51 protein in tumor tissues from patients after interval debulking surgery (IDS)." (PMID 41199843, 2025). "Differential analysis of the TCGA‐OSCC dataset revealed significant overexpression of RAD51 in tumour tissues compared to normal controls as illustrated by the volcano plot." (PMID 41350246, 2025). "RAD51 inhibitor (RAD51i) B02 was tested in p-SCCATRi by cell cycle analysis and in ovo tumor growth of chorioallantoic membrane (CAM) xenografts, complemented by apoptosis staining." (PMID 41387887, 2025). "A practical way forward is to pair genomic scars with functional HRD readouts—notably, RAD51 foci assays calibrated for FFPE—as well as activity-based functional tests that capture live HR proficiency across tumor types." (PMID 41440218, 2025). "In xenograft studies, the combination of B02 and cisplatin markedly reduced tumor growth, demonstrating that RAD51 inhibition can potentiate chemotherapy–induced damage." (PMID 41190241, 2025). "UNI66, another inhibitor of BRD4, suppresses HR by inhibiting BRD4-mediated transcription of CtBP-interacting protein (CtIP) and RAD51, thereby inducing synthetic lethality in PARP1-deficient cells and enhancing tumor sensitivity to PARPis." (PMID 41190241, 2025). "Studies suggest that Amuvatinib can reduce tumor cell drug resistance by inhibiting RAD51 protein expression." (PMID 40746357, 2025).
tumor (continued). "Western blot analysis showed increased levels of BCKDK, p‐RNF8S157, and RAD51 proteins in tumor tissues compared to their adjacent normal tissues, suggesting enhanced activity of the BCKDK/p‐RNF8/RAD51 regulatory pathway in clinical tumor tissues." (PMID 40298908, 2025). "To further assess the synergistic effect in vivo, we utilized an MMTV‐PyMT mouse TNBC model, which showed an enhanced BCKDK/p‐RNF8/RAD51 axis in tumor tissues compared to normal compartments." (PMID 40298908, 2025). "The Myr-NE tumor xenografts showed a notable decrease in RAD51 and Ku70 proteins compared to Myricetin." (PMID 40552278, 2025). "Homologous recombination is involved in tumor chemoresistance, and RAD51 is one of hub components of the homologous recombination-mediated double-strand DNA break repair machinery." (PMID 39865088, 2025). "One possibility is that NACT-induced exogenous DNA damage triggers an increase in RAD51 expression, making tumor cells less responsive to chemotherapy and promoting the subsequent development of platinum resistance recurrence." (PMID 41199843, 2025). "SFPQ and RAD51 expression were positively associated across tumor lineages (Pearson r = 0.625; p = 6.9×10−1 ), consistent with a model in which SFPQ supports RAD51 expression." (PMID 40964404, 2025). "Elevated RAD51 expression correlated with tumor progression and a poorer prognosis in both TCGA and CGGA datasets." (PMID 39990235, 2025). "And accumulative evidence has demonstrated that RAD51 inhibition sensitizes tumor cells to DNA-damaging agents." (PMID 39865088, 2025). "RAD51, a central recombinase, drives homologous pairing and strand exchange, and its inhibition has been shown to induce senescence and suppress tumor growth." (PMID 41281944, 2025). "In xenograft models, cisplatin monotherapy inhibits tumor growth by only 33%, whereas its combination with RAD51 inhibitors reduces tumor volume by over 50%, indicating strong synergy and a marked reversal of resistance." (PMID 40949156, 2025). "Consistent with in vitro results, RNF8 phosphorylation and RAD51 protein levels were increased in Olaparib‐treated tumor samples and were rescued by BCKDK knockdown." (PMID 40298908, 2025). "This positions RAD51 as a pivotal regulator of tumour‐immune interactions and a promising immunomodulatory target." (PMID 41350246, 2025). "In our study, AQB was found to inhibit CBPt-induced expression of key proteins in the HRR cascade, including MRE11, RAD50, P-CHK1, P-CHK2, and RAD51, leading to DNA damage accumulation and promoting tumor cell death." (PMID 41353219, 2025). "Accumulating evidence correlates elevated RAD51 expression and HR-related function with poorer prognosis, metastasis and resistance to chemotherapy and radiotherapy in various tumour types, including PDAC, which remains a significant unmet medical need." (PMID 40091075, 2025). "Among these, B02 remains the most widely used RAD51 inhibitor, known to sensitize tumor cells to radiation and chemotherapy while sparing normal cells, and has been broadly applied in preclinical models to study HR repair inhibition." (PMID 41387887, 2025). "As the HR pathway is only active after DNA double-strand breaks in proliferating cells, we evaluated RAD51 IHC after the exclusion of low-γH2AX (DNA damage marker)- or low-geminin (G2/S phase marker)-expressing tumor samples." (PMID 38725623, 2024). "When tumor cells are exposed to DNA-damaging agents, RAD51 is recruited to the sites of DNA damage and forms distinct foci in a proficient HR repair environment." (PMID 39156700, 2024). "BRCA1, BRCA2, and RAD51 are all key participants in DNA damage repair and show a promoting role in tumor metastasis." (PMID 38983866, 2024). "Imatinib enhances the sensitivity of tumor cells to radiation therapy by suppressing the RAD51 protein involved in the Homologous Recombination pathway." (PMID 39029056, 2024).
tumor (continued). "These encompass tumor-specific gene therapy delivery and intracellular antibody-based RAD51 targeting, among others." (PMID 39352803, 2024). "We previously reported that none of the PARPi-resistant BRCA2-deficient tumours restored RAD51 IRIF12, whereas 64% (29/45) of the BRCA1-deficient tumours became RAD51 IRIF+." (PMID 38789420, 2024). "Onvansertib also decreased the number of RAD51-positive tumor cells in vivo, indicative of reduced HR-mediated DNA repair." (PMID 39039067, 2024). "In these tumours, we also determined RAD51 ionizing radiation-induced foci (IRIF) to distinguish Homologous Recombination (HR)-dependent from -independent mechanisms of PARPi resistance." (PMID 38789420, 2024). "When treated with Gemcitabine (GEM), a Rad-51 inhibitor, there are better outcomes because of the presence of higher levels of chemotherapy at tumor sites, thereby reducing gastrointestinal side effects." (PMID 38899244, 2024). "Downregulation of RAD51 expression reduces the DNA damage repair capacity of tumor cells, thereby enhancing the efficacy of tumor gene toxic therapy." (PMID 39156700, 2024). "Anti-angiogenic agents down-regulate HR genes such as BRCA1/2 and RAD51 through inducing hypoxia in the tumour microenvironment and interactions with other transcriptional repressors." (PMID 39135999, 2024). "RAD51 protein expression levels were significantly lower in the DLD-1 hATM (−/−) tumor xenografts compared to that in the parental HR-proficient DLD-1 tumor xenograft." (PMID 38807759, 2024). "Data presented here advance 3E10 as a unique inhibitor of a critical DDR protein, RAD51, which can also be used as a highly tumor-specific agent." (PMID 39352803, 2024). "The next-generation sequencing (NGS) of case 1 confirmed deletion mutations in SMARCA4, RAD51 and TSC2, and the tumor mutation burden (TMB) was 0.96 mutations/Mb." (PMID 38877473, 2024). "The expression of CPNE3, YAP1, CYR61, and RAD51 proteins in tumor tissue samples from 100 randomly selected patients with GC was examined using continuous-section IHC labeling." (PMID 38493426, 2024). "The RAD51-FFPE score in these samples was determined by analyzing the accumulation of RAD51 protein at sites of DNA damage in proliferating tumor cells." (PMID 37725154, 2023). "RAD51 and γ-H2AX foci formation assays illustrated that deficient HR repair in the first surgery tumor samples was complemented by the primary RAD51D mutation but not with the secondary RAD51D mutation." (PMID 37833926, 2023). "The 4 risk genes of LAMA4, POLA2, RAD51, and TYMS showed significant differences in the expression of normal and tumor tissues, and the 4 genes showed high expression in tumor tissues." (PMID 37051625, 2023). "The percentages of proliferating tumor cells positive for RAD51 and BRCA1 foci were evaluated using an immunofluorescence assay, as a readout of homologous recombination repair status." (PMID 37686585, 2023). "IHC staining and quantitative analysis revealed that the phosphorylation of ATR and Chk1 and the expression of Rad51 were inhibited in tumours derived from the scaRNA2 KD cells." (PMID 37775817, 2023). "In a previous study, RAD51 expression was found higher in tumor cells than in normal tissues and elevated RAD51 expression was associated with poor differentiation, lymphatic metastases, and higher relapse rates in clinical study." (PMID 37798649, 2023). "To investigate if HRD is more prevalent in specific tumor types, we stratified clinicopathologic characteristics by HR-status as determined by the RAD51-FFPE test." (PMID 37725154, 2023). "An in vivo tumor model confirmed the RAD51 inhibitor’s antitumor activity and synergistic antitumor activity with sorafenib in HCC." (PMID 37175611, 2023). "Further in vivo verification of the anti‐tumor effect of co‐targeting RAD51 and KRAS is required in the future." (PMID 36262061, 2023). "The RECAP test is a RAD51-based functional HRD test using viable tumor tissue for the identification of HRD in BC." (PMID 37725154, 2023).
tumor (continued). "Out of the 67 tumor samples for which a final RAD51-FFPE score was determined, 27 samples were categorized as HRD." (PMID 37725154, 2023). "In our MPM cohort, tumor samples with a low number of RAD51 foci displayed a low number of BRCA1 foci, likely corroborating defects in the HR repair pathway." (PMID 37686585, 2023). "Our studies demonstrate that BCDX2 orchestrates RAD51 assembly on single-stranded DNA for replication fork protection and double strand break repair, in reactions that are critical for tumour avoidance." (PMID 37344587, 2023). "Low efficiency in RAD51 focus formation predicted the response in PDX models showing tumour regression and complete response, while the models responding with a stable disease display a high RAD51 score." (PMID 37029129, 2023). "Subsequently, RT-qPCR results showed that relative to Pem alone, Pem + ITF2357 markedly decreased the expression levels of HDAC2 and Rad51 in tumor tissues of mice while increasing that of miR-130a-3p were increased." (PMID 36793108, 2023). "Previous studies have shown that cediranib is a highly effective VEGFR (KDR) inhibitor and that cediranib targets BRCA2/RAD51 in tumor cells." (PMID 37355516, 2023). "Here, we find that the yeast ubiquitin ligase Bre1 and its human homolog RNF20, a tumor suppressor, function as recombination mediators, promoting Rad51 filament formation and subsequent reactions via multiple mechanisms independent of their ligase activities." (PMID 37230987, 2023). "A promising approach is the use of functional HRD tests which evaluate the HR capability of tumor cells by measuring RAD51 protein accumulation at DNA damage sites." (PMID 37725154, 2023). "The tumor suppressor BRCA2 participates in DNA double-strand break repair by RAD51-dependent homologous recombination and protects stressed DNA replication forks from nucleolytic attack." (PMID 36702902, 2023). "We observed that all the analyzed tumor samples formed RAD51 foci 2 h after irradiation and were therefore classified as HR-proficient according to the RECAP assay." (PMID 36672427, 2023). "The protein expression level of RAD51 in tumor tissues is significantly higher than that of normal tissues." (PMID 37286702, 2023). "This approach provides an opportunity to target tumors with mutations in tumor suppressor genes such as BRCA1, BRCA2, and RAD51, where loss of function results in the tumorigenic consequences of deficient homologous recombination." (PMID 37628794, 2023). "In total, twenty-three individual HNSCC tumors were tested with the RECAP assay, and in all the analyzed tumor samples RAD51 foci formation was observed in more than 50% of Geminin-positive cells." (PMID 36672427, 2023). "Transcription factors engaged in Rad51 expression is crucial for the response of tumor cells to DNA-damaging agents." (PMID 35875146, 2022). "Our approach notably enabled the identification of over-expressed tumour suppressor gene RAD51 in GBM compared to healthy controls, which has recently been shown to be a target for inhibition to enhance radiosensitivity of GBM cells during treatment." (PMID 35931958, 2022). "Our second observation is that tumor cells pre-exposed to radiation can be more radiation-resistant, which is mediated by HR and hence RAD51." (PMID 35992802, 2022). "The RAD51 inhibitor Cpd-4 alone showed dose-dependent anti-tumor efficacy, with TGIs of 34.3% and 85.6% at 30 mg/kg and 100 mg/kg, respectively." (PMID 35646698, 2022). "SRF and EXOSC3 expression levels were lower in tumor tissues than in control tissues, while RAD51 and EXOC1 were significantly higher in tumor tissues." (PMID 35096059, 2022). "Relative to control (vehicle treatment), tumor sizes in mice treated with RAD51 inhibitor, cisplatin and combination of RAD51 inhibitor and cisplatin were reduced by 30%, 59% and 71%, respectively (p < 0.04)." (PMID 36428789, 2022).
tumor (continued). "It has been well-established that Rad51 functions as a promising predictor for the identification of PARP inhibitor-sensitive tumors in multiple tumor types." (PMID 35875146, 2022). "RAD51, which is closely involved in the HR process, is often overexpressed in chemoresistant radioresistant human tumor tissues." (PMID 36548864, 2022). "We further demonstrated that BMI1/RAD51 axis activation is necessary to prevent cisplatin-induced DNA damage and that treatment of patient-derived xenografts with a RAD51 inhibitor sensitizes tumor-initiating cells to cisplatin." (PMID 35110528, 2022). "The impact of RAD51 inhibitor on efficacy of DNA breaking agent was also investigated in a subcutaneous tumor model of EAC." (PMID 36428789, 2022). "Collectively, Rad51 is a promising therapeutic target for developing anti-tumor strategies, waiting for deeper investigation." (PMID 35875146, 2022). "While many researchers indicated an insignificant role of HR in DNA repair in tumor cells, we observed a correlation between the proliferative activity of cells and the expression level of the main factor of HR-mediated DNA repair, RAD51." (PMID 35992802, 2022). "RAD51 overexpression promoted genome instability, and the dynamics of RAD51 filament formation and stability were vital for tumor suppression by maintaining genomic stability." (PMID 36233194, 2022). "The tumour suppressor PALB2 stimulates RAD51-mediated homologous recombination (HR) repair of DNA damage, whilst its steady-state association with active genes protects these loci from replication stress." (PMID 36269050, 2022). "Our previous data also demonstrated that inhibition of HR, through chemical as well as transgenic inhibition of recombinase RAD51, reduces genomic instability as well as tumor growth in a subcutaneous model of EAC." (PMID 36428789, 2022). "It had been previously shown that ER stress reduces DNA double-strand break (DSB) repair and increases radiosensitivity of tumor cells via proteasomal degradation of Rad51." (PMID 35361260, 2022). "In olaparib-treated tumor models, the percentage of RAD51-positive cells was 1.25 ± 0.25% in the four PARPi-sensitive models and 66.54 ± 2.70% in the 14 PARPi-resistant models (p < 0.0001)." (PMID 36091750, 2022). "PTEN, as a tumor suppressor, functions in the maintenance of genome integrity by regulating RAD51 and CHK1 activity." (PMID 35725817, 2022). "Consistent with the presence of basal replication stress in CRC tumor cells, these cells depended on RAD51 for proper DNA replication in unperturbed conditions." (PMID 35969531, 2022). "It has been found that the fusion of Rad51 promoter to diphtheria toxin A gene impair the initiation of multiple tumor types, such as breast and cervical tumor, with minimal effect on normal epithelial cells." (PMID 35875146, 2022). "By upregulating ATR-CHK1 signaling, the RAD51 inhibitors increased surface PD-L1 levels in various tumor cells, suggesting a potential combination of RAD51 inhibitors with PD-1/PD-L1 blockade." (PMID 35646698, 2022). "In conclusion, we have shown here a specific role of RAD51 in replication fork progression in cells having replication stress, which, interestingly, is a distinctive of most tumor cells." (PMID 35969531, 2022). "An important consequence of VEGFR inhibition is tumor hypoxia, a state that has been linked to HR defects via the downregulation of BRCA1, BRCA2, and RAD51." (PMID 35681619, 2022). "Specifically, the deeper mechanisms by which Rad51 regulate metabolic rewiring of tumor cells need to be studied, including how Rad51 regulates the expression of glycolytic proteins and activates specific downstream signaling pathways." (PMID 35875146, 2022). "They synergistically work with CHK1 to repress DSB-induced RAD51 foci, thus impairing the HR process and enhancing RS in tumor cells." (PMID 35875060, 2022).